IL6 (interleukin 6)
Diseases named in the same sentence as IL6 in open-access papers (continued):
Sharing a sentence is not in itself a finding about the gene and the disease.
inflammatory bowel disease (continued). "The study showed that LPS was identified by Toll like receptor 4 (TLR4) to release TNF-α, IL-1 beta and IL-6 and other cytokines, which mediate and promote the occurrence of inflammatory bowel disease (IBD)." (PMID 30075775, 2018). "Furthermore, in the classical aetiology of CAC, the initial development of inflammatory bowel diseases (IBD) such as colitis ulcerosa and Crohn’s disease are also associated with increased IL-6 level in circulation." (PMID 29695802, 2018). "The transcriptional factor NF-κB is known to regulate the level of TNF-α, IL-6, and IL-1β during the progression of inflammatory bowel disease." (PMID 29483924, 2018). "The proinflammatory cytokine, interleukin-6 (IL-6), plays a critical role in many chronic inflammatory diseases, particularly inflammatory bowel disease." (PMID 30200658, 2018). "Intestinal NPY, PYY, and PP are reported to be abnormal in patients with inflammatory bowel disease and its animal models with increased plasma IL-6." (PMID 29429048, 2018). "A significantly increased IL-6 production was reported in stimulated monocytes from patients with active inflammatory bowel disease (IBD) in comparison with samples from inactive disease phases or healthy control individuals." (PMID 29748708, 2018). "In a similar fashion, also patients with Inflammatory bowel disease (IBD) had intestinal proinflammatory EVs with elevated levels of IL-6, IL-8, and TNF on mRNA as well as protein level compared to healthy controls." (PMID 28491866, 2017). "CMV infection in the intestine of individuals with inflammatory bowel diseases has been frequently correlated with an increased production of IL-6, and CMV shedding was associated with higher IL-6 levels in vaginal swabs of ART-suppressed HIV-infected women." (PMID 28241080, 2017). "Interleukin-6 (IL-6) is known to increase TJ permeability via PI3K pathway in inflammatory bowel diseases." (PMID 28694783, 2017). "LPS-induced cytokines IL-1β, IL-6, and TNFα, which are also expressed in inflammatory bowel disease, are reported to down-regulate PXR and CYP genes in vivo." (PMID 27760163, 2016). "The differentiated macrophages are potent producers of key inflammatory cytokines such as TNFα, IL-1β and IL-6 in inflammatory bowel disease 50,51." (PMID 25754842, 2015). "On the other hand, in combination with the pro-inflammatory cytokine IL-6, TGF-β can induce differentiation of Th17 cells, a T cell subset with a prominent pathogenic role in inflammatory bowel diseases." (PMID 24465791, 2014). "Recent investigations support the important role of interleukin-6 (IL-6) in inflammatory bowel disease, showing that these cytokine levels are increased in patients with this inflammatory process." (PMID 24518681, 2014). "Interleukin 6 (IL-6) and tumor necrosis factor alpha (TNFα) are proinflammatory cytokines that play a critical role in inflammatory bowel disease, as well as in colorectal tumorigenesis." (PMID 24120915, 2014). "Among the substances most commonly used in the treatment of inflammatory bowel disease is tocilizumab, which operates on the inhibition of IL-6." (PMID 24518681, 2014). "It is also well known, for example, that IL-6 is very high in inflammatory bowel disease (IBD) including ulcerative colitis (UC) and Crohn’s disease (CD), and exists in foci specific manner, suggesting its major roles in IBD pathology." (PMID 23520506, 2013). "IL-6, known for its potent immuno-stimulatory and pro-inflammatory effects in inflammatory bowel disease, is produced by macrophages, lymphocytes, and intestinal epithelial cells." (PMID 19450258, 2009). "Given the current paucity of data, we reflected on the potential of IL-6 inhibitors such as tocilizumab and olamkicept based on immunopathogenic considerations and available clinical data in patients with inflammatory bowel disease (IBD), in whom clinical response or remission was induced." (PMID 39857830, 2025).
inflammatory bowel disease (continued). "In a dextran sodium sulfate (DSS)-induced murine model of colitis, DSS treatment resulted in a significant increase in the expression levels of pro-inflammatory cytokines such as IL-1β, TNF-α, and IL-6, which play key roles in the pathogenesis of inflammatory bowel disease (IBD)." (PMID 40051564, 2025). "Studies have shown that SCFAs produced by Firmicutes can inhibit pathogen growth, suppress pro-inflammatory factors (like tnf-α and il-6) expressions, enhance intestinal epithelial cells’ tight junctions, stabilize the intestinal environment, and alleviate inflammatory bowel diseases." (PMID 40943507, 2025). "Additionally, IL-6 can promote the development of inflammatory bowel disease through the STAT3 signaling pathway." (PMID 40053041, 2025). "Cytokines, including IL‐1β, IL‐6, and TNF‐α, are expressed at relatively higher levels in the intestinal tissues of patients with UC, and MPO‐mediated damage is associated with some disorders in people, including inflammatory bowel disease." (PMID 40586619, 2025). "FC is a specific marker for intestinal mucosal inflammation and is routinely measured in stool samples, while CRP and interleukin-6 (IL-6) are nonspecific markers of inflammation associated with inflammatory bowel disease–related inflammation." (PMID 40831567, 2025). "Furthermore, target modulation of various cytokines, including IL-6, has been proposed as a therapeutic option in inflammatory bowel disease." (PMID 39062898, 2024). "At the global level, neither inflammatory bowel diseases nor inflammatory cytokines (IL-6 and IL-6Rα) have been found to be causally associated with brain cortex structures." (PMID 37153572, 2023). "In their study of inflammatory bowel diseases in humans, the researchers found that the expression of the inflammatory cytokines IL-6, TNF-α, and IL-1β were, respectively, upregulated 2.266, 0.962, and 3.468 fold, in both Crohn’s disease and ulcerative colitis compared to healthy individuals." (PMID 38116527, 2023). "MMP-9, IL-6, and TNF-α are pathogenic factors playing a crucial role in the progression of inflammatory responses in the gastrointestinal tract (for instance in patients with inflammatory bowel disease), causing an increase in intestinal permeability." (PMID 37997993, 2023). "It has been reported that LPS could stimulate the TLR4-NF-κB signaling pathway to induce the release of TNF-α, IL-1β, and IL-6, which are inflammatory cytokines in inflammatory bowel disease." (PMID 37125181, 2023). "Therapeutic strategies for the blockade of IL-6 are used for Inflammatory bowel disease (IBD)." (PMID 36524122, 2022). "CXCL11, referred to as interferon-inducible T-cell alpha chemoattractant (I-TAC), could drive Th1 cells to secrete proinflammatory cytokine IL-6 in the inflammatory bowel disease." (PMID 36003333, 2022). "It has been proven that IL6 expression in inflammatory bowel disease may be derived from the activation of a variety of cells, including monocytes, intestinal epithelial cells and lamina propria monocytes." (PMID 36371157, 2022). "A recent study reported that IL-6, as a pro-inflammatory cytokine, could induce intestinal epithelial barrier dysfunction and play a role in the pathological process of inflammatory bowel disease (IBD)." (PMID 32276396, 2020). "Secondary cytokines such as TNF-α, IL-1β, and IL-6 are known to increase the presence of inflammatory cells in the colon tissue in response to primary Th1/Th17 immune responses in inflammatory bowel disease (IBD) thereby synergistically drawing the inflammatory milieu." (PMID 31683524, 2019). "Others have reported that active CMV infection could be often detected in the intestine of individuals with inflammatory bowel diseases and may contribute to the inflammatory process through virus-induced IL-6." (PMID 28241080, 2017).
inflammatory bowel disease (continued). "IL-6 signalling is important for host response to pathogen, but the over-expression of this cytokine is one of the major factors involved in the pathogenesis of different inflammatory diseases such as inflammatory bowel disease." (PMID 28477627, 2017). "IL6 is a previously known causative gene of inflammatory bowel disease but not other gastrointestinal disease phenotypes." (PMID 25933025, 2015). "In addition, BMP7 administration conferred intestinal mucosal protection and reduced systemic IL-6 expression levels in an inflammatory bowel disease model." (PMID 25132736, 2014). "IL-6, which links inflammatory bowel disease (IBD), AGE-RAGE, JAK/STAT, PI3K/Akt, cytokine–cytokine receptor interaction, and EGFR-TKI-resistance signaling pathways, was upregulated by the SYN treatment versus the PL treatment." (PMID 40563358, 2025). "For 6 of these genes, a role in inflammatory bowel disease is supported by other criteria: GWAS associations with nearby SNPs (ANKRD55, LPP, PDLIM7), experimental perturbation (CCDC50, VCAM1), association with measured protein levels (IL6, VCAM1), or drug effects (IL6, VCAM1)." (PMID 40996888, 2025). "Salivary biomarkers as calprotectin, lactoferrin, and cytokines as TNF and IL-6 can be used to track inflammatory bowel disease (IBD), which indicates damage to the intestines and systemic inflammation." (PMID 40005360, 2025). "In the context of inflammatory bowel disease (IBD), IL-6 has been shown to contribute to chronic intestinal inflammation." (PMID 40872523, 2025). "Besides being highly expressed in pancreatic tissue, Reg proteins were also found to be inducible in the intestinal tract, particularly Reg1 and Reg3 subfamily proteins that were induced by IL6/IL22 in inflammatory bowel disease (IBD) for mucosal regeneration through STAT3 activation." (PMID 39857608, 2024). "In inflammatory bowel disease, activated DCs could release the inflammatory cytokines such as IL-6, IL-12 and tumor necrosis factor (TNF-α) by up-regulating the pattern recognition receptors [Toll-like receptor (TLR) 2 and TLR4], MHC class II molecules, and costimulatory molecules (CD40 and CD86)." (PMID 37670381, 2023). "IL-6 levels were significantly higher in patients with IBD with a positive family history in comparison to those without a family history of inflammatory bowel disease (6.3 pg/mL vs. 5.2 pg/mL, p = 0.0197)." (PMID 37762896, 2023). "Pro-inflammatory cytokines are generally upregulated in inflammatory bowel disease (IBD) including TNFα and IL-6." (PMID 38106420, 2023). "Administration of antibodies against TNF-α, IL-12/23p40, and IL-6 produced by innate immune cells is effective for treating inflammatory bowel disease (IBD)." (PMID 36845090, 2023). "Considering that TG expression with the risk alleles in the colon correlated with the development of ICRPs in MDs, TG-mediated activation of the IL-6 amplifier in the intestine may contribute to the high concurrent occurrence of thyroidal disease and inflammatory bowel disease in human patients." (PMID 37519997, 2023). "It is well known that IL-6 is an important proinflammatory cytokine involved in the development of inflammatory bowel diseases (IBD), whereas considerable evidence suggest the important role played by IL-2 in maintaining a healthy immune response in the gut." (PMID 36432588, 2022). "Intervention with AG490 (a highly selective JAK2 inhibitor) in a rat model of inflammatory bowel disease (IBD) significantly decreased the levels of IL-6 and IL-17A and increased the levels of IL-10, suggesting a protective effect on IBD." (PMID 35590365, 2022). "Several pro-inflammatory cytokines, including IL-6, IL-1β, and interferon-γ, have been shown to induce DNA methylation, making epigenetic modulation of ion transport components a newly emerging area of interest for a deeper understanding of the pathogenesis of inflammatory bowel disease (IBD)." (PMID 35626748, 2022).
inflammatory bowel disease (continued). "Interestingly, some of these mediators such as IL-6 and TNF-α are involved in the pathogenesis of inflammatory bowel disease, promoting gut damage and loss of intestinal barrier integrity, while IL-10 reduces the inflammation typically associated with this pathology." (PMID 35854319, 2022). "IL-6 up-regulates the expression of intercellular adhesion molecule one, a key adhesion molecule in inflammatory bowel disease (IBD), by inducing the activation of NF-κB." (PMID 33841156, 2021). "Correspondingly, the inhibition of IL-6 transsignaling, wherein the complex of IL-6 and sIL-6R can stimulate cells that do not express IL-6R (such as endothelial cells and smooth muscle cells), is sufficient to block disease in mouse models of inflammatory bowel disease and RA." (PMID 34156295, 2021). "IL-6 is also highly elevated in the synovia of RA patients, and in the intestinal mucosa of inflammatory bowel disease (IBD) patients." (PMID 31379810, 2019). "In humans STAT3 represents one of the disease loci for Crohn's and inflammatory bowel disease (IBD), and most likely relates to the capacity of Stat3 to promote intestinal barrier function and integrity in response to IL6, IL11 and IL22 exposure." (PMID 20478049, 2010). "Recent studies have shown that matrine can diminish inflammatory responses and oxidative stress by blocking the IL-6/STAT3 signaling pathway, thereby attenuating intestinal mucosal damage in rats with inflammatory bowel disease (IBD)." (PMID 39902829, 2025). "Upon activation, it induces the expression of pro-inflammatory cytokines such as interleukin (IL)-6, IL-12, IL-23, and tumor necrosis factor-α (TNF-α), all of which are central to the inflammatory cascade in inflammatory bowel disease (IBD)." (PMID 41007813, 2025). "Butyrate specifically exhibits potent anti-inflammatory effects in intestinal macrophages by inhibiting nitric oxide, IL-6, and IL-12 production through HDAC-dependent pathways, suggesting therapeutic potential for inflammatory bowel disease (IBD)." (PMID 40943341, 2025). "During inflammatory bowel disease (IBD), inflammatory fibroblast subsets upregulate secretion of chemokines like IL-6, CXCL1, and CCL2, promoting neutrophil and macrophage infiltration." (PMID 41465375, 2025). "Inflammatory bowel disease (IBD) and many other inflammatory disorders are characterized by elevated expression of pro-inflammatory cytokines, such as TNF-α, IL-6 and IL-1β." (PMID 40391223, 2025). "Some phages have been shown to reduce pro-inflammatory cytokines such as IL-6, TNF-α, and IL-1β, thus alleviating systemic inflammation in diseases like inflammatory bowel disease (IBD) and rheumatoid arthritis." (PMID 40427029, 2025). "In patients with inflammatory bowel disease (IBD), 5-HT also increases Nicotinamide adenine dinucleotide phosphate (NADPH) -dependent reactive oxygen species (ROS) production and upregulates IL-6 and IL-8." (PMID 40761882, 2025). "For instance, in inflammatory bowel disease (IBD), an overactive cytokine response leads to chronic inflammation in the gut, driven by excessive production of TNF-α, IL-1β, and IL-6, which contribute to tissue damage and immune dysregulation." (PMID 40364844, 2025). "These inflammation-enhanced models can mimic conditions like inflammatory bowel disease leading to CRC, allowing testing of candidates such as NSAIDs, IL-6/JAK-STAT inhibitors, or novel PAR-2 antagonists in a controlled setting." (PMID 40647462, 2025). "This was evident in a study involving inflammatory bowel disease (IBD) in mice, where MSC administration led to diminished levels of pro-inflammatory cytokines, including IL-6, in inflamed colon tissue." (PMID 39015561, 2024).
inflammatory bowel disease (continued). "High IL-6 expression in the intestinal mucosa induces expression of the S100A9 protein and activation of NFκB signaling in inflammatory bowel disease." (PMID 39337548, 2024). "Upregulated during inflammatory bowel disease, MMP9 maintained the mucosal–epithelial integrity and increased proinflammatory cytokines such as IL-6." (PMID 39337548, 2024). "IL-6, TNF-α, IL-1β, and IL-10 serve as pivotal pathological mediators in inflammatory bowel disease." (PMID 39187810, 2024). "The superpathway of L-cysteine biosynthesis (mammalian) can produce L-cysteine to downregulate the production of pro-inflammatory cytokines like IL-6, TNF-α, interferon-γ (IFN-γ), and IL-1β in inflammatory bowel disease (IBD)." (PMID 38675747, 2024). "Previous in vitro investigations had shown that both IL-6 and TNF were necessary to trigger TNFR2 in CRC cells, perhaps indicating a physiological microenvironment of several cytokines in inflammatory bowel disease (IBD) or IBD-associated CRC." (PMID 36672682, 2023). "In patients with inflammatory bowel disease, IL-24 is capable of inducing the expression of proinflammatory cytokines such as TNF-α and IL-6 as well as induction of inflammation and immune cell infiltration during tissue damage." (PMID 36806964, 2023). "In another inflammatory disease like inflammatory bowel disease curcumin have cellular targets interaction with NF‐κB, JAKs/STATs, MAPKs, TNF‐α, IL‐6, PPAR, and TRPV1." (PMID 37324924, 2023). "It is still unknown whether targeting the IL-6 signaling pathway would have a causal effect on NAFLD through several drugs targeting this pathway that have been approved or displayed clinical potency for metabolic diseases, inflammatory bowel disease (IBD), and liver and gastrointestinal cancer." (PMID 35747747, 2022). "In a separate inflammatory bowel disease (IBD) murine model, OXTR knock-out mice displayed an increased number of pro-inflammatory cytokine transcripts encoding for TNF-α, IL-1β, and IL-6 and exhibited shorter villi and crypts in the intestinal mucosa, a sign of chronic inflammation." (PMID 38983562, 2022). "Among these, the core pathway related to UC was inflammatory bowel disease (KEGG:05321), containing the hub targets of IL6, TNF, RELA, and STAT3." (PMID 36382627, 2022). "On protein level, the key proteins like IL-6, TNF-α, NFKBp65, and STAT3 of the inflammatory bowel disease pathway had the same change trend." (PMID 36382627, 2022). "In several studies, it has been shown that inflammatory bowel disease results in increased concentrations of proinflammatory cytokines, including tumor necrosis factor alpha (TNF-α), interleukin (IL)-1β, IL-6, and IL-17." (PMID 34754319, 2021). "EXO of intestinal lumen aspirates of inflammatory bowel disease IBD patients carry pro-inflammatory factors including TNF-α, IL6, and IL8 in levels higher than that of healthy controls." (PMID 35011677, 2021). "IL-6, IL-6/STAT3 signaling mediates various diseases, such as inflammatory bowel disease, Castleman disease, osteoarthritis, and osteoporosis." (PMID 34833909, 2021). "In an in-vitro study, a significant reduction was seen in several inflammatory biomarkers including tumor TNF-α, IL-1α, IL-6, IL-8, T-cell interferon-gamma (IFN-γ), and IL-2, in the presence of ≥10 μg/ml garlic extract in inflammatory bowel disease." (PMID 30683061, 2019). "Various studies showed that IL-1, IL-6, and TNF-α play a key role in invoking inflammatory cells and tissue damage in inflammatory bowel diseases." (PMID 31143692, 2019). "H and mH suppressed the production of the inflammatory mediators nitric oxide (NO), interleukin (IL)-6, IL-8, and tumor-necrosis factor (TNF)-α, which are most highly activated in inflammatory bowel disease (IBD)." (PMID 29673161, 2018). "In contrast, IL-6 depletion exacerbated autoimmune cholangitis in conjunction with hepatic B cell and CD8+ T cell accrual, but ameliorated inflammatory bowel disease." (PMID 30450101, 2018).